PTX3 (pentraxin 3)
Diseases named in the same sentence as PTX3 in open-access papers (continued):
Sharing a sentence is not in itself a finding about the gene and the disease.
breast carcinoma (continued). "Accordingly, PTX3 expression was reported to be elevated in bone metastases of breast cancer, whereby this pentraxin has been proposed to be involved in the inflammation-associated osteolytic complications of breast cancer." (PMID 38068970, 2023). "Compared to various breast cancer cells, PTX3 expression and its response to TGF‐β1 were significantly higher in BCAFs." (PMID 35090088, 2022). "Complement activation along with angiogenesis have also been noted in glioblastoma through PTX-3 modulation, similar to prostate and breast carcinomas." (PMID 36499628, 2022). "As a key molecule of bone metabolism, PTX3 overexpression can affect osteoclast differentiation and promote bone metastasis of breast cancer and gastric cancer." (PMID 35982954, 2022). "The overexpression of PTX3 is a poor prognosis sign in lots of cancer types such as lung cancer, cervical cancer, colorectal cancer, pancreatic cancer, breast cancer, gastric cancer, melanoma, and squamous cell carcinoma of the head and neck." (PMID 35982954, 2022). "In breast cancer, the PTX3 expression is correlated with the poorly differentiated aggressive triple negative breast cancer." (PMID 36555812, 2022). "Serum NF-κB, TNF-α, sTRAIL, IL-6, PTX-3, PCT, and serum CRP levels were measured using enzyme-linked immunosorbent assay (ELISA) in 40 patients with breast cancer, 40 patients with colon cancer and 30 healthy controls." (PMID 33776564, 2021). "A study from 2009 found that overexpression of PTX3 reduced angiogenic activity in human breast carcinoma cells due to its capacity to neutralize FGF-2." (PMID 34048179, 2021). "Up-regulation of PTX-3 gene expression has been described in aggressive breast cancer and distant bone metastases." (PMID 33776564, 2021). "In breast cancer, PTX3 was induced by hypoxia and correlated with poor prognosis, inducing stem-cell-like characteristics and metastasis formation." (PMID 33917524, 2021). "It was found that the most increasing parameters of breast cancer risk were high levels of NF-κB, TNF-α, IL-6, PCT, PTX-3, and CRP." (PMID 33776564, 2021). "The ssGSEA analysis showed that the genes with differential expression by SH3RF3 and PTX3 overexpression were coordinately expressed in breast cancer cell lines." (PMID 32427938, 2020). "It was found that PTX3 expression was significantly increased in various tumors, including lung cancer, pancreatic cancer, glioma and breast cancer." (PMID 31957804, 2020). "Increased PTX3 gene expression was reported in ovarian cancer with stromal signature, in aggressive breast cancer with distant bone metastases, in prostate cancer, in glioblastoma, in anaplastic thyroid carcinoma, and in soft tissue liposarcoma." (PMID 32345771, 2020). "PTX3 is known to mediate the differentiation of breast cancer cells into BOLCs cells and the formation of HA crystals." (PMID 33584725, 2020). "Specifically, we found that breast cancer tumors with a high BOLCs amount and high PTX3 expression were characterized by several HA microcalcifications." (PMID 33584725, 2020). "PTX3 was also found to be an oncogenic phosphoinositide 3-kinase signaling critical target, involved in promotion of stem cell-like traits in basal-like breast cancers." (PMID 32345771, 2020). "In this study, we show that the scaffold protein SH3RF3 is highly expressed in breast cancer CSCs and reveal its function to enhance the cancer cell stemness by regulating PTX3." (PMID 32427938, 2020). "Through this system, PTX3 inhibits tumor metastasis, tumor growth and tumor angiogenesis in melanoma, breast cancer, prostate cancer and multiple myeloma." (PMID 33013829, 2020). "Based on these evidences, PTX3 can be considered a new possible marker for poor differentiated breast cancer." (PMID 33584725, 2020). "We observed a significantly decreased expression of Nav 1.5 after rBmK AGAP treatment which correlated with decreased expression of p-p65/NF-κB, TNF-α, and PTX3 in breast cancer cells." (PMID 30740360, 2019).
breast carcinoma (continued). "rBmK AGAP treatment decreased PTX3 expression in vitro and in vivo which correlated with decreased stem-like features, epithelial-mesenchymal transition, migration, and invasion of breast cancer cells." (PMID 30740360, 2019). "We realized a decreased expression of IKKα, p-p65/NF-κB, and TNF-α in both breast cancer cells which correlated with decreased PTX3 expression." (PMID 30740360, 2019). "Western blot confirmed the successful down-regulation of PTX3 in both breast cancer cells which correlated with decreased expression levels of Oct4, Sox2, and N-cadherin but increased expression of E-cadherin compared with control." (PMID 30740360, 2019). "In a previous study, it was observed that NF-κB was necessary to drive PTX3 expression to regulate the propagation of stem cell-like traits in breast cancer cells." (PMID 30740360, 2019). "Breast and gastric cancer cell lines have been reported to express PTX3, and the exogenous protein promoted migration of breast cancer cells and macrophages." (PMID 31787987, 2019). "This suggests BmK AGAP activity in decreasing breast cancer cell stemness and epithelial-mesenchymal transition to target PTX3." (PMID 30740360, 2019). "We further examined PTX3 expression in breast cancer tissues of patients: patient one (first-grade tumor, molecular subtype HER2); patient two (second-grade tumor, molecular subtype BLBC); and patient three (third-grade tumor, molecular subtype BLBC)." (PMID 30740360, 2019). "In basal-like breast cancers, PTX3 was found to be a critical target of oncogenic phosphoinositide 3-kinase signaling and NF-κB-dependent pathways, and to be associated with PI3K-induced stem cell-like traits." (PMID 31019517, 2019). "In this present study, to investigate the effects of rBmK AGAP on PTX3 expression in human breast cancer cells, we first determined the inhibitory concentration value (IC50) of rBmK AGAP." (PMID 30740360, 2019). "The results showed a similar significantly increased PTX3 expression in breast cancer tissues as the tumor advanced in stages compared with the normal breast tissues." (PMID 30740360, 2019). "In this present study, to investigate the effect of BmK AGAP on breast cancer cells, we first examined PTX3 expression in MCF-10A, MDA-MB-231, BT549, and MCF-7 cells by qPCR, western blot, and immunofluorescence staining." (PMID 30740360, 2019). "Long pentraxin-3 (PTX3) is an inhibitor of various FGFR ligands, among them FGF2 and FGF8b, which have both been found to be implicated in breast cancer development." (PMID 30011957, 2018). "The elevated expression and secretion of PTX3 in breast cancer cells promote tumor bone-metastatic properties." (PMID 28489600, 2017). "By knocking down PTX3, the siRNA transfected cells displayed decreased PTX3 levels and suppressed the migratory ability of breast cancer cells." (PMID 27377307, 2016). "Recent studies have demonstrated that exogenous PTX3 enhanced the migratory potential of macrophages to breast cancer cells and PTX3 silencing blocked macrophage mobility toward breast cancer cells." (PMID 27377307, 2016). "We previously reported that bone metastatic breast cancer cell-derived PTX3 enhanced osteoclastogenesis by upregulating RANKL expression in OBs." (PMID 27458153, 2016). "PTX3 has recently been found to affect cell spreading and metastasis formation in breast cancer 31 and other tumours." (PMID 26010680, 2015). "The loss-of-function assay indicated that PTX3 contributed to CDDP- and 5FU-induced protumor effects in drug-susceptible and resistant breast cancer cells, respectively." (PMID 26124179, 2015). "This indicates that PTX3 is expressed in bone metastatic human breast cancer cells, which are predominantly osteolytic." (PMID 24457902, 2014). "PTX3 expression was also up-regulated in a bone metastatic breast cancer cell line and further enhanced by pro-inflammatory cytokine TNFα." (PMID 24457902, 2014).
breast carcinoma (continued). "Next, we performed scratch assays to examine the role of PTX3 in the migration of breast cancer cells." (PMID 24457902, 2014). "Together, these results suggest that TNFα regulates PTX3 expression in bone metastatic breast cancer cells at both mRNA and protein levels." (PMID 24457902, 2014). "Although PTX3 is expressed in a variety of cells and induced by inflammatory conditions, the role of PTX3 in breast cancer malignancy and metastasis is unclear." (PMID 24457902, 2014). "The present study was undertaken to assess the presence and significance of PTX3 in human breast cancers in the context of bone metastasis, and its related osteolytic function." (PMID 24457902, 2014). "This study found that PTX3 expression was up-regulated in distant bone metastases of breast cancer compared to lung, liver, and brain metastases in 64 human breast cancer patients." (PMID 24457902, 2014). "Administration of PTX3 promoted the migratory potential of breast cancer cells and the mobilization of macrophages, a precursor of osteoclasts (OCs), toward breast cancer cells." (PMID 24457902, 2014). "In line with this, we observed that exogenous PTX3 enhanced the migratory potential of macrophages to breast cancer cells and PTX3 silencing blocked macrophage mobility toward breast cancer cells." (PMID 24457902, 2014). "We observed that increased expression of PTX3 in bone metastatic tumor in human breast cancer patients was accompanied by the direct secretion of extracellular PTX3 by bone metastatic breast cancer cells." (PMID 24457902, 2014). "The expression level of PTX3 in bone metastasis sample was significantly higher than that of lung, liver, or brain metastases in breast cancer patients." (PMID 24457902, 2014). "PTX3 silencing in MDA-MB-231 cells displayed reduced migration of macrophages toward breast cancer cells." (PMID 24457902, 2014). "Approximately 1.0 × 105 macrophages migrated in controls, but a higher level of cell migration (approximately 2.0 × 105) was observed in the presence of PTX3, suggesting that PTX3 enhanced the migration of macrophages to breast cancer cells." (PMID 24457902, 2014). "Despite the apparent clarity of PTX3’s metastasis-promoting effects in breast cancer, the complex role of peripheral PTX3 requires further investigation, as it is closely associated with estrogen receptor (ER) status in breast cancer at both the mRNA and protein levels." (PMID 41479916, 2025). "For instance, in breast cancer, PTX3 inhibits dihydrotestosterone- and FGF8b-driven cell proliferation, while elevated PTX3 levels, induced by TNF-α stimulation in a bone metastatic breast cancer cell line, promote cell migration, macrophage chemotaxis, and subsequent osteoclast differentiation." (PMID 41479916, 2025). "In addition, the macrophage CEPBD/PTX3 axis contributes to metastasis, invasion, and stemness in breast cancer cells." (PMID 40990024, 2025). "PTX3 is correlated with ER status in breast cancer at both mRNA and protein levels." (PMID 41479916, 2025). "Similarly, the downregulation of PTX3 using an antitumor analgesic peptide in breast cancer cells reduced cancer cell stemness, EMT, migration, and invasion." (PMID 39594709, 2024). "In addition, treating breast cancer with CDDP promoted the level of CEBPD in CAFs as well as tumor-associated macrophages (TAMs) and led to chemoresistance through pentraxin 3 (PTX3)-induced invasion, metastasis, and stemness." (PMID 36776299, 2023). "The NF-kB signaling and PTX3 provide biomarkers for a precision medicine approach to breast cancer and may represent potential druggable targets for the future, in combination with PARPis." (PMID 36555812, 2022). "However, the synthetic PTX3 peptide inhibitors RI37 and AD9 and the PTX3NA protein dramatically inhibited PTX3‐induced signalling and downstream gene activation and inhibited the protumour effects of sphere formation and migration/invasion in breast cancer." (PMID 35090088, 2022).
breast carcinoma (continued). "Additionally, PTX3 is exclusively expressed in basal-like breast cancer via PI3K-AKT- NF-κB signaling and promotes stem-cell-like traits." (PMID 35615145, 2022). "In addition, PTX3 has pleiotropic roles in different types of cancer, such as gastric cancer, breast cancer, glioma, and prostate cancer." (PMID 34202354, 2021). "PTX3 involves in the epithelial–mesenchymal transition in melanoma and breast cancer." (PMID 32984316, 2020). "In this study, we found SH3RF3 could upregulate the expression of Pentraxin 3 (PTX3) to promote stem-like traits of breast cancer cells." (PMID 32427938, 2020). "Pentraxin 3 (PTX3) is overexpressed in the bone metastasis of breast cancer when compared with lung, liver and brain metastasis, because PTX3 induces osteolytic bone metastasis by facilitating cancer cell migration and macrophage migration to cancer cells and increasing osteoclast formation." (PMID 32674405, 2020). "The present study was designed to test the hypothesis that scorpion venom analgesic peptide, BmK AGAP inhibits cancer stemness and epithelial-mesenchymal transition by down-regulating PTX3 expression in breast cancer." (PMID 30740360, 2019). "The expression of PTX3 is high in several malignancies, including breast cancer." (PMID 30740360, 2019). "The expression of PTX3 is said to correlate with NF-κB in breast cancer." (PMID 30740360, 2019). "PTX3 increased the migratory capacity of breast cancer cells." (PMID 27377307, 2016). "Moreover, although a high PTX3 abundance has been observed in the serum of several cancers, including liposarcoma, prostate cancer, lung cancer and breast cancer, the precise role of PTX3 in tumorigenesis remains largely uninvestigated." (PMID 26124179, 2015). "Furthermore, PTX3 silencing using siRNA-specific siRNA prevented breast cancer cell migration, macrophage Chemotaxis, and subsequent OC formation." (PMID 24457902, 2014). "In addition, we investigated the potent role of PTX3 in promoting the migratory capacity of breast cancer cells, and Chemotaxis of macrophages and precursors of OCs toward breast cancer cells." (PMID 24457902, 2014). "In addition, elevated expression of PTX3 by TNFα led to enhanced OC formation, implying the distinct role of PTX3 in osteolytic bone metastasis of breast cancer cells." (PMID 24457902, 2014). "To test this possibility, we examined whether PTX3 regulates breast cancer cell viability and/or proliferation." (PMID 24457902, 2014). "However, evaluation of clinical cancer tissue samples of breast cancer patients revealed a weak correlation between PTX3 level and survival (GSE12276) (p=0.052)." (PMID 24457902, 2014). "Given that the pro-inflammatory cytokine TNFα up-regulated expression of PTX3, we hypothesized that increased production of PTX3 in breast cancer cells may support cell proliferation and migration." (PMID 24457902, 2014). "Elevated expression of PTX3 was correlated with poor survival in patients with breast cancer." (PMID 24457902, 2014). "In conclusion, we demonstrated the clinical and biological function of PTX3 in bone metastatic breast cancer, providing evidence that PTX3 has an important role in OC differentiation and activation, leading to the osteolytic properties of breast cancer metastasized to bone." (PMID 24457902, 2014). "We were able to show that FXYD3 and PTX3 expression is associated with poor overall patient survival in SCC patients and LAD1, SLC7A5, SLPI, NID2, SPOCK1 and SULF1 correlated significantly with impaired pCR in breast cancer patients." (PMID 23251436, 2012). "Additionally, PTX3 is a differentially expressed gene in aggressive breast cancer cell lines." (PMID 41479916, 2025). "In addition, Ptx3 can promote cell migration in breast cancer and head and neck cancer." (PMID 36633805, 2023). "However, CEBPD‐associated PTX3 regulation has not been examined in detail regarding its clinical or epidemiological characteristics in various cancers, including breast cancer." (PMID 35090088, 2022).
breast carcinoma (continued). "This evidence suggested that Nav 1.5 may play a role in PTX3 expression in breast cancer." (PMID 30740360, 2019). "Thus, inactivation of NF-κB signaling may decrease PTX3 expression in breast cancer cells by decreased p-p65/NF-κB and TNF-α." (PMID 30740360, 2019). "The role of PTX3 overexpression in breast cancer remains unclear." (PMID 30740360, 2019). "Assessment of PTX3 expression status in breast tumors provides clinically useful prognostic information as a potential biomarker in bone metastatic breast cancer, and indicates that the PTX3 pathway might be a novel therapeutic target for breast cancer metastases to bone." (PMID 24457902, 2014). "Specifically, in this study, we perform immunohistochemical and bioinformatic analyses to investigate the possible prognostic role of vimentin, SDF-1, BMP-2, BMP-4, PTX3, OPN, RANKL, and Runx2 on a large cohort of breast cancer patients." (PMID 39859358, 2025). "PTX3 is regulated by SH3RF3 through JNK-JUN pathway, thus enhancing breast cancer stem cell properties." (PMID 41479916, 2025). "Transcriptomic data from TEPA treated breast cancer cells also displays changes in the immune-related genes (including IL6, IL6R, IL15, CXCL1, CXCL8, and PTX3) in breast cancer." (PMID 37480151, 2023). "Accordingly, gene expression, Western blot and ELISA analyses showed higher PTX3 expression and secretion in TNBC cell lines when compared to ER+/PR+ and HER2+ breast cancer cells." (PMID 37749607, 2023). "When expressed by CAFs, PTX3 acts as a CD44 ligand and contributes to the migration of breast cancer cells." (PMID 37563650, 2023). "In addition, suggesting that PTX3 may represent a cancer biomarker of breast cancer progression." (PMID 35090088, 2022). "Papila and colleagues compared serum values of NF-ƙB, PTX-3, IL-6, CRP, TNF-α, and sTRAIL (soluble TNF-related apoptosis-inducing ligand) and PCT (procalcitonin) in 40 individuals diagnosed with breast cancer, 40 with colon cancer, and 30 health controls." (PMID 36499628, 2022). "For example, PTX3 affects tumor proliferation and apoptosis by interacting with the PI3K/AKT/mTOR signaling pathway in lung cancer and breast cancer." (PMID 32984316, 2020). "Here, the authors show that the scaffold protein SH3RF3 enhances the stem-like properties of breast cancer by facilitating activation of the JNK-JUN pathway and PTX3 expression." (PMID 32427938, 2020). "Here, decreased expression of PTX3 post rBmK AGAP treatment correlated with decreased IKKα, p65/NF-κB, TNF-α, and NF-κB DNA binding and transcription activity inhibiting breast cancer cell stemness and epithelial-mesenchymal transition." (PMID 30740360, 2019). "rBmK AGAP inhibited breast cancer cell stemness, EMT, migration, and invasion by down-regulating PTX3 through NF-κB and Wnt/β-catenin signaling Pathway in vitro and in vivo." (PMID 30740360, 2019). "Immunohistochemical analysis was performed to evaluate the expression of vimentin, BMP-2, BMP-4, RANKL, Runx2, OPN, PTX3, and SDF-1, while Kaplan—Meier plots were used to assess their prognostic impact on overall survival in a dataset of 2976 breast cancer patients." (PMID 39859358, 2025). "Moreover, NF-ƙB expression was positively correlated with PTX-3, PCT, CRP, and IL-6 in patients with breast cancer and colon cancer." (PMID 36499628, 2022). "Our current results suggest that the C‐terminus of PTX3 directly interacts with the N‐terminus of CD44, consequently activating metastasis/invasion and stemness through the involved genes by activating the AKT, ERK1/2 and NF‐κB pathways in breast cancer cells." (PMID 35090088, 2022). "The PTX-3 and PCT levels were significantly higher in colon cancer compared to breast cancer." (PMID 33776564, 2021). "PTX3 interacts with the PI3K/AKT/mTOR signaling pathway or the fibroblast growth factor-2/receptor system to regulate tumor cell proliferation, apoptosis, and metastasis in lung cancer, breast cancer, melanoma, prostate cancer, and multiple myeloma." (PMID 34745101, 2021).